VTRNA2-1 (vault RNA 2-1)
Synonyms: vtRNA2; hvg-5; CBL-3; hsa-mir-886; nc886; pre-miR-886; CBL3; MIR886; MIRN886; svtRNA2-1a
Gene: Gene (Ensembl biotype vault_RNA) on chromosome 5 (136,080,470 to 136,080,597, reverse strand). Ensembl gene ENSG00000270123.
Diseases named in the same sentence as VTRNA2-1 in open-access papers:
VTRNA2-1 is named in the same sentence as 23 diseases in open-access papers, as found by Europe PMC text mining. Sharing a sentence is not in itself a finding about the gene and the disease. The quoted sentences say what the papers report.
viral infection (2 papers, 2015 to 2020). "Since PKR plays a critical role in the host innate defense against viral infection, it is possible that IAV-induced vtRNA2-1 promotes the viral replication by inhibiting PKR activation." (PMID 26490959, 2015).
acute lymphoblastic leukaemia (1 paper, 2025). "Recently, VTRNA2-1 hypermethylation at birth was suggested to be a precursor of paediatric acute lymphoblastic leukaemia with biomarker potential." (PMID 39799337, 2025).
cervical cancer (1 paper, 2021). A primary or metastatic malignant neoplasm involving the cervix. "Furthermore, E2F1, a cell cycle regulator, was described as a direct transcriptional regulator of vtRNA2-1 in cervical cancer cells (Liet al., 2017)." (PMID 34354812, 2021).
renal carcinoma (1 paper, 2021). A carcinoma arising from the epithelium of the renal parenchyma or the renal pelvis. "Yet, vtRNA2-1 has been also proposed as an OG in ovarian, thyroid, endometrial, cervical and renal cancer (Ahnet al., 2018;Huet al., 2017;Leeet al., 2016;Leiet al., 2017;Liet al., 2017;Yeganeh & Hernandez, 2020)." (PMID 34354812, 2021).
tumor (15 papers, 2014 to 2025). "Likewise, VTRNA2-1, an imprinted gene that appears to act as a tumor suppressor and linked to various types of cancer, was associated in the colon tissue with a haplotype that overlaps its promoter and ICRs." (PMID 33067439, 2020). "Interestingly, it has previously been suggested that VTRNA2-1’s putative tumor suppressor function is linked to phosphorylation of the RNA sensitive protein kinase receptor (PKR), a key event in interferon signaling." (PMID 26473932, 2015). "Multiple studies have pointed to the possible role of vtRNA2-1 in many different cancers, interestingly acting as a tumor suppressor or oncogene depending on the cancer type." (PMID 38612882, 2024). "VTRNA2-1 has tumour suppressor gene properties, as it regulates cell growth via inhibition of protein kinase RNA-activated (PKR)." (PMID 36708485, 2023). "VTRNA2-1 is a putative tumour suppressor and modulator of innate immunity." (PMID 34246240, 2021). "VTRNA2-1 has also been suggested to be a tumor suppressor in other cancers." (PMID 26473932, 2015).
cancer (9 papers, 2013 to 2025). A tumor composed of atypical neoplastic, often pleomorphic cells that invade other tissues. "vtRNA1-1 also regulates autophagy by associating with RBP p62, whereas vtRNA2-1 functions as a tumor suppressor by interacting with protein kinase R in a wide range of cancer cells." (PMID 41373720, 2025). "For example, vtRNA2-1 inhibits proliferation of several cancer cells, including colon, lung, breast, skin, cervical, and oral cancers, while vtRNA1-1 regulates apoptosis and cancer invasion." (PMID 41373720, 2025). "Due to its importance for cancer biology, vtRNA2-1 transcriptional regulation was recently more investigated." (PMID 34354812, 2021). "Remarkably, at seven of these, peripheral blood DNA methylation at baseline was significantly associated with later cancer; three (SPATC1L, VTRNA2-1, and DUSP22) were significantly associated with multiple types of cancer." (PMID 29310692, 2018). "Interestingly, this interaction is crucial for vtRNA2-1 maturation suppression in this type of cancer." (PMID 38612882, 2024).
VTRNA2-1 also shares sentences with these, for which no sentence is quoted: cholangiocarcinoma (2 papers); gastric cancer (2); prostate carcinoma (2); thyroid cancer (2); acute myeloid leukemia (1); Barrett esophagus (1); breast carcinoma (1); chylomicron retention disease (1); esophageal carcinoma (1); esophageal squamous cell carcinoma (1); familial lipoprotein lipase deficiency (1); hyperglycaemia (1); infection (1); leukemia (1); lymphoma (1); Obesity (1); type 1 diabetes (1).